UBC (ubiquitin C)
Diseases named in the same sentence as UBC in open-access papers (continued):
Sharing a sentence is not in itself a finding about the gene and the disease.
non-small cell lung carcinoma (1 paper, 2024). A group of at least three distinct histological types of lung cancer, including non-small cell squamous cell carcinoma, adenocarcinoma, and large cell carcinoma. "It is worth noting that these observations align with the existing literature that has reported the overexpression of UBB and UBC in various cancer types, including PC and non-small-cell lung cancer." (PMID 38473264, 2024).
pancreatic disease (1 paper, 2017). "Pathways associated with these retrieved potential modifiers indicated that immune system is likely involved and that Ubiquitin C is the central node linking CF to liver and pancreatic disease." (PMID 28339466, 2017).
pituitary adenomas (1 paper, 2014). "Also, the present study clearly demonstrated that ubiquitin C (UBC) was the key node among four NFPA subtypes to suggest that oxidative/nitrative stress might also be involved in cell-cycle dysregulation in human pituitary adenomas." (PMID 25539738, 2014).
pneumonia (1 paper, 2024). An acute, acute and chronic, or chronic inflammation focally or diffusely affecting the lung parenchyma, caused by an infection in one or both of the lungs (by bacteria, viruses, fungi, or mycoplasma.). "In the 18 reference COVID-19-associated pneumonia autopsies the estimated viral load normalized by the UBC (ubiquitin C) reference gene mRNA varied in a broad range: the median normalized viral load in the sample set amounted to 0.0233 [0.0016; 0.2232]." (PMID 39497823, 2024).
pulmonary TB (1 paper, 2025). "To identify the most stable HKGs for analyzing material from patients with pulmonary TB, we selected eight genes—ACTB, B2M, GAPDH, HPRT1, PPIA, RPL13A, YWHAZ and UBC—that are most commonly employed as reference genes in clinical studies." (PMID 41303702, 2025).
Right ventricular hypertrophy (1 paper, 2021). In this case the right ventricle is more muscular than normal, causing a characteristic boot-shaped (coeur-en-sabot) appearance as seen on anterior- posterior chest x-rays. "None of the mice—UBC-Cre/ERT2 or kcnk3fl/fl developed either elevated RVSP or right ventricular hypertrophy." (PMID 34065088, 2021).
Splenomegaly (1 paper, 2011). Abnormal increased size of the spleen. "Indeed, macroscopic examination of tamoxifen-treated Vhlfloxed-UBC-Cre-ERT2 mice revealed marked splenomegaly, an indicator of increased activity of the oxygen-VHL/PHD/HIF sensing pathway, as seen in Phd2 deficient and Phd1:Phd3 double knock-out mice." (PMID 21811636, 2011).
Stroke (1 paper, 2015). Sudden impairment of blood flow to a part of the brain due to occlusion or rupture of an artery to the brain. "In the future, significant proteins including UBC, CUL3, APP, NEDD8, JUP, SIRT7, etc., can be potent drug targets for first aid and emergency treatment within 24 h post-stroke." (PMID 26679092, 2015).
teratoma (1 paper, 2017). A non-seminomatous germ cell tumor characterized by the presence of various tissues which correspond to the different germinal layers (endoderm, mesoderm, and ectoderm). "In the UbC-iC9-TKDA3-4 hiPSC-NS/PCs grafted group, however, the graft rapidly increased in size, growing into a teratoma containing embryonic elements of all three primary germ cell layers." (PMID 28262544, 2017).
urothelial carcinoma (1 paper, 2025). A malignant neoplasm derived from the transitional epithelium of the urinary tract (urinary bladder, ureter, urethra, or renal pelvis). "In the PPI network specific to nonpapillary urothelial carcinoma, network B, we identified GNB1, RHOA, UBC, and FPR2 as hub proteins, which were involved in the PI3K/AKT signaling pathway." (PMID 41342186, 2025).
tumor (66 papers, 2008 to 2026). "UBC encodes ubiquitin C, which regulates multiple biological functions, and its expression is associated with tumor progression." (PMID 29018224, 2017). "Therefore, further exploring the functional regulation of LASP-1 and its interacting proteins by Ubiquitin C-associated ubiquitination pathway in different tumours will help us better understand the molecular mechanism of carcinogenesis associated with LASP-1 and its interactors." (PMID 28266596, 2017). "We observed a significantly higher UBC expression in tumor tissues when compared to normal adjacent tissues (p = 0.0318)." (PMID 38473264, 2024). "The aim of the study was to investigate the methylation status of CDKN1, CDKN2A, MYC, Smad3, SP1, and UBC genes in tumor tissue (control-normal tissue) in 50 patients (37 men and 13 women) with HPV-negative HNSCC." (PMID 38540340, 2024). "The aim of the study was to evaluate promoter methylation of CDKN1, CDKN2A, MYC, Smad3, SP1, and UBC genes in tumor tissue of HNSCC patients." (PMID 38540340, 2024). "We next asked how we can translate this information to the tumours developed in PGK-NRASG12V or UBC-NRASG12V cohorts." (PMID 39112713, 2024). "All tumor sections showed strong staining for ubiquitin C (UBC), except in areas with necrosis, indicating that each tumor had good RNA preservation." (PMID 36674782, 2023). "For this, UBC-Cre-ERT2-tdTomato mice were bred with Snai1fl/fl mice to prevent Snail1 reactivation in the tumour stroma." (PMID 37516803, 2023). "The results of WGCNA showed that the turquoise and blue modules, which are highly related to the eutopic endometrial cell group and the ectopic endometrial cell group, all contained tumor related genes, such as UBC, UBA52, RPS27A, PIK3CB, IRS1, and CEACAM1." (PMID 33868805, 2021). "Expression of UBC in non-tumour tissues was negatively correlated with AST and total bilirubin levels (Spearman's rho= -0.39 and -0.31; P=0.017 and 0.065, respectively), but positively correlated with albumin levels (Spearman's rho= 0.36; P=0.03)." (PMID 32132870, 2020). "Mapping the integration site of the UbC-mCherry cassette to the locus of the tumour suppressor candidate ING3 prompted us to further investigate the homozygous lethal phenotype." (PMID 31905726, 2019). "Three positive control probes, POLR2A, PPIB and UBC were applied to FFPE sections from a range of tumour types in FFPE whole-face (prospective collection) or TMA (retrospective collection) formats and evaluated semi-quantitatively and by image analysis." (PMID 29212158, 2017). "Compared with shRNA-NC group, combined silencing of UBB and UBC (shRNA-B4/C2) inhibited 51.51% of tumor volume, which was more effectively than that of shRNA-B4-transfected group (27.12%) or shRNA-C2-transfected group (45.05%)." (PMID 25820571, 2015). "This network also exhibited focus hubs containing NFκB, ERK1/2, UBC, p38MAPK, and HNF4α, all which regulate inflammation, and survival and proliferation of tumor cells." (PMID 24283668, 2013). "Furthermore, there was a notable increase in UBC expression in lymph node metastatic tissues in comparison to tumor tissues (p < 0.001)." (PMID 38473264, 2024). "UBB or UBC protein was required for some cancer cells to keep tumor features, like myeloma cells." (PMID 37684377, 2023). "Inhibiting the ubiquitin UBC in tumors of UBB silencing led to tumor regression." (PMID 37350942, 2023). "Activation of WNT signaling in osteoclasts, osteoblasts, and cancer cells resulted in their conversion to tumor-suppressive cells with secretomes enriched with Hsp90ab1, enolase 1 (Eno1), moesin (MSN), and ubiquitin C (Ubc), which acted as atypical tumor-suppressors." (PMID 35994202, 2022).
tumor (continued). "Up-regulation of UBC inhibited the occurrence of lysosomal autophagy, which may result in inhibition of normal cell apoptosis and promoting tumor cell proliferation." (PMID 32294625, 2020). "Firstly, the evidence that downregulation of UBC occurred in different cell lines, both normal and tumor-derived, suggested that it might constitute a widespread regulatory response to Ub overexpression." (PMID 31811203, 2019). "DepMap demonstrated that the deletion of UBC, DARS2, and DCXR significantly inhibited tumor cell proliferation, asserting their roles in maintaining tumor growth." (PMID 39990673, 2025). "The results of the analyses conducted for the TCGA cohort revealed a significantly higher mRNA expression of UBB, UBC, and CTNNB1 in tumor tissues compared to normal tissues (p < 0.0001 for all)." (PMID 38473264, 2024). "In contrast, the expression levels of UBB, UBC, and CTNNB1 in tumor versus normal tissues varied between the GEO cohorts, ranging from being unchanged to being slightly overexpressed or downregulated." (PMID 38473264, 2024). "Among them, the actions of 6 tumor-suppressing proteins, ENO1, Ubiquitin C (UBC), Moesin (MSN), heat shock protein 90ab1 (HSP90ab1, aka HSP90β), Calreticulin (CALR), and Histone H4 (H4), have been documented with a proposed mechanism 12-14." (PMID 37056934, 2023). "Previous studies for iTSCs showed that MSC CM, generated by the activation of Wnt and PI3K signaling pathways, were enriched with extracellular tumor-suppressing proteins such as CALR, ENO1, HSP, MSN, and UBC." (PMID 36943734, 2023). "In the TCGA database, five transcripts for the selected tumor-suppressing proteins (CALR, ENO1, HSP, MSN, and UBC) were significantly upregulated in OS cells." (PMID 36943734, 2023). "Eight hub genes (CDK1, EGFR, UBC, MYC, CCNB1, RHOB, CDC6, and CDC20) have tumor suppressor functions, while five hub genes (CDK1, EGFR, FYN, UBC, and CCNB1) are protein kinases as well." (PMID 35632527, 2022). "No significant changes in the expression of housekeeping genes, including beta-actin (ACTB), beta-2-microglobulin (B2M) and ubiquitin C (UBC), were detected in LUAD and UCEC tumor samples when compared to their respective normal samples." (PMID 36084949, 2022). "To access the mechanism of anti-tumor, anti-inflammatory actions of YS MSC CM, we selected five tumor suppressors (Hsp90ab1, calreticulin, histone H4, polyubiquitin C, and enolase 1) based on our previous whole-genome proteomics analysis." (PMID 35804814, 2022). "Relative expression of the five genes EFP, HERC5, UBA1, UBC and USP18, which are related to ISGylation, was quantified and compared between HCC tumour and adjacent non-tumour tissues." (PMID 32132870, 2020). "In tumor tissue samples, the CV of EEF1A1 (6.12) was the second highest compared with UBC and GAPDH." (PMID 26222051, 2015). "CVs of GAPDH, UBC and EEF1A1 across ischemia time points and patients in normal and tumor colorectal tissue." (PMID 26222051, 2015). "Studies have demonstrated that the α-fetoprotein (AFP), carcinoembryonic antigen (CEA), ubiquitin C (UbC), murine albumin (mAlb), prostate-specific antigen (PSA) and the glucose transporter gene 1 (GTI-1.3) promoters all lead to tumor-specific hNIS expression." (PMID 23420532, 2013). "Tumour tissue and normal tissue group of five candidate reference genes (CASC3, CDKN1B, POLR2A, PUM1 and UBC) were statistically equivalent to within ± 1.5." (PMID 21806841, 2011).
tumor (continued). "The FC in gene expression of each marker in tumour samples relative to healthy controls was determined using the 2− ΔΔCt method normalised to the average of 7 housekeeping genes (YWHAZ, CYC1, SDHA, TBP, GAPDH, UBC and 18s RNA)." (PMID 41034696, 2025). "Extracellular UBC presents anti-tumor action to multiple lines of breast cancer cells and pancreatic cancer cells, although the mechanism of its tumor-suppressive capability is not yet elucidated." (PMID 37056934, 2023). "Together with the tumor-suppressing proteins such as CALR, ENO1, HSP, MSN, and UBC, which were enriched in tumor-suppressive CM, six recombinant proteins, such as HISTONE H4, PPIB, GJA1, CPE, S100A11, and PCOLCE, were identified as extracellular tumor-suppressing proteins." (PMID 36943734, 2023). "Among the 25 MRGs exhibiting differential expression between the normal and tumor tissues, only MAP1LC3B, PINK1, PARK2, UBB, and UBC were significantly downregulated in the tumor tissues, while expression of the other genes was significantly upregulated in the tumor samples." (PMID 38155968, 2023). "In addition, a network of EZH2 and its interacting proteins (UBC, CDK1, HDAC1, SUZ12, EED) was found to participate in miR-26a-mediated tumor progression." (PMID 34381816, 2021). "The Δ133TP53 probe, a positive control probe to ubiquitin C (UBC) to check RNA quality, and a DapB negative control probe were hybridized to 15 tumours with the highest Δ133TP53β expression." (PMID 31431617, 2019). "The results of our analysis proved that the expression of reference genes in our cohort of patients, including only endometrioid histotype and carefully selected and balanced according to their tumor grade, was dependent on tumor grade for B2M, GAPDH, H3F3A, GUSB, HPRT1, POLR2A and UBC." (PMID 25473950, 2014). "Then, UBC modulated STAT5A and HSF1 in the WNT and the MAPK signaling pathways to inhibit DNA repair through the mediation of HIST2H2BE and to induce antiapoptosis through the mediation of HSPB1, which might finally facilitate tumor growth." (PMID 30344796, 2018). "Furthermore, for a multifunctional protein like ubiquitin C (UBC), whose activity is heavily regulated at the post‐translational level, mRNA abundance may not reliably reflect its functional state in the complex tumour microenvironment." (PMID 41354645, 2025). "The amount of neoantigen expressed in each tumor cell varies greatly, and LV proviruses are susceptible to silencing after incorporation into the genome (this depends greatly on the promoters; CMV, sv40, and other viral promoters are prone to silencing compared with non-viral UBC and PGK)." (PMID 34632444, 2021). "However, the tumor-suppressing action of extracellular polyubiquitin C has not been reported." (PMID 34830748, 2021). "Then, UBC could modulate STAT5A and CEBPA in the WNT and the MAPK signaling pathways to inhibit DNA repair through the dysregulation of HIST2H2BE and to induce the accumulation of autoimmune defects through the dysregulation of IGF2, which might ultimately facilitate tumor growth." (PMID 30344796, 2018). "Organs from an egg without a tumor were used to test eight primers for cross‐reactivity with the chicken cells, namely B2M, HMBS, ALTB, TBP, SDHA, YWHAZ, and UBC." (PMID 40443053, 2025). "Two major transcriptional regulators, the hepatocyte nuclear factor 4, alpha (HNF4A) and ubiquitin C (UBC) genes, had no predictive expression value in HCC-R tumor tissues." (PMID 24377043, 2013). "Thus, UBC and PLK-1 on one hand and negative control siRNA1 and siRNA2 on the other hand defined a range among which candidate genes were ranked according to their impact on CTL-mediated tumor lysis." (PMID 25691366, 2015).
cancer (47 papers, 2010 to 2026). A tumor composed of atypical neoplastic, often pleomorphic cells that invade other tissues. "The majority of the remaining genes from the set of 32 genes, even if they demonstrate stable mRNA level in certain cancer types, have many pseudogenes or high mutation rate (for example, UBC is above the 99th percentile in BRCA)." (PMID 30881377, 2019). "Usually, UBC is implicated in protein degradation, cell cycle regulation, DNA repair and is identified to contribute towards cancer metastasis." (PMID 28349958, 2017). "Therefore, understanding the roles of UBB and UBC in β-Catenin ubiquitination is of paramount importance in deciphering the molecular mechanisms underlying cancer development and exploring potential therapeutic targets." (PMID 38473264, 2024). "No previous study has exhibited a direct link between polyubiquitin-C (encoded by UBC) and cancer." (PMID 28152021, 2017). "Interestingly, the UBC gene dominates most of the targeted genes associated with CVDs network, so its role in the cancer pathway warrants further investigation." (PMID 27703845, 2016). "This collective body of evidence highlights the potential therapeutic significance of targeting UBB and UBC in cancer treatment and emphasizes the multifaceted factors contributing to the aggressive behavior of various cancer types." (PMID 38473264, 2024). "Remarkably, upregulation of UBC has also been found in many human cancer specimens; however, the relationship between UBC and DLBCL needs further research." (PMID 36281462, 2022). "Of note, an upregulation of UBB and UBC has also been detected in many human cancer specimens, when compared with paired normal adjacent tissues." (PMID 32751694, 2020). "Both UBB and UBC were found to be upregulated in several cancers and their high expression levels seemed to be essential to sustain the high proliferation rate of cancer cells and to support their ability to overcome increasing cellular stresses." (PMID 32751694, 2020). "We found 18 genes (ubiquitin C (UBC) excluded) were universally included across all cancer-type networks." (PMID 28765560, 2017). "In this analysis, UBC expression was found in all stages, suggesting that its function if disrupted can result in uncontrolled cell division, a key feature of cancer." (PMID 24369052, 2013). "A lentiviral vector containing the firefly luc2 gene conjugated to a human ubiquitin C promoter was constructed to generate stable bioluminescent cancer cell lines." (PMID 20186331, 2010). "Experimental evidence support UBC’s roles in autophagy and signaling in cancer cells and attachment of ubiquitin types to other proteins modulate DNA repair, cell-cycle communication, lysosomal and protein degradation, and kinase activation, among other events." (PMID 35814389, 2022). "Importantly, the growth of LLC1 carcinoma tumors was significantly faster in UbC-Ppm1d transgenic mice compared with either Ppm1dfl/fl or Ppm1dFes-cre mice." (PMID 34131120, 2021). "UBC represents a ubiquitin gene (ubiquitin C) and has been described in cancers infrequently." (PMID 31974418, 2020). "Several reports demonstrated the pro-survival role of UBB and UBC in cancer cells." (PMID 32751694, 2020). "UBB and UBC upregulation in several cancers is widely documented." (PMID 32751694, 2020). "Moreover, the knockdown of two ubiquitin-encoding genes including polyubiquitin B (UBB) and polyubiquitin C (UBC) enhanced the efficacy of therapeutic irradiation against cancer." (PMID 30893775, 2019). "Although the UBC gene is neither a key gene nor a targeted gene, it dominates all of the targeted genes; whether this fact implies that the UBC gene acts as a master regulator in the cancer pathway deserves further experimental investigation." (PMID 26817825, 2016).